ZAP70 (zeta chain of T cell receptor associated protein kinase 70)
Diseases named in the same sentence as ZAP70 in open-access papers (continued):
Sharing a sentence is not in itself a finding about the gene and the disease.
leukemia (18 papers, 2013 to 2025). A malignant (clonal) hematologic disorder, involving hematopoietic stem cells and characterized by the presence of primitive or atypical myeloid or lymphoid cells in the bone marrow and the blood. "ZAP70 and EGCG displayed high binding affinity (Kd = 0.6207 μM), and EGCG dose-dependently induced caspase-mediated apoptosis in ZAP70-expressing leukemia cells, whereas ZAP70-deficient cells were resistant to EGCG treatment." (PMID 29843451, 2018). "This case-control study aimed to unravel whether the ZAP70 missense variant (rs104893674 (C > A)) underpinning mixed-phenotype leukemia." (PMID 39113054, 2024). "In particular, EGCG triggered caspase-mediated apoptosis in ZAP-70-expressing leukemia cells in a dose-dependent manner, whereas EGCG treatment was ineffective against P116 ZAP-70-deficient cells." (PMID 37446908, 2023). "The course of CLL depends on the clinical stage and some molecular factors, such as CD38 or ZAP70 expression on leukemia cells or deletion 17p leukemia." (PMID 35158937, 2022). "We observed that pre-treatment of leukemia cells with AZA was connected to increased Lck and Zap70 phosphorylation in CD4+ CAR T cells upon contact with the pre-treated leukemia cells." (PMID 34750374, 2021). "To support the role that ZAP-70 expression plays in gefitinib-induced apoptosis, we examined four leukemia/lymphoma cell lines for their sensitivity to gefitinib treatment." (PMID 25275600, 2014). "Based on standard definitions, ZAP-70+ CLL samples were defined as having ≥20% of their leukemia cells expressing ZAP-70,3 but changing the threshold of positive cells did not influence the results." (PMID 25275600, 2014). "By activating either the T-cell receptor for T-CLL or the B-cell receptor for B-CLL, CCR7 induced expression of the protein tyrosine kinase, ZAP70, increasing leukemia cell actin polymerization and migration, suggesting an alternative CCR7-linked actin-dependent migratory pathway in leukemia." (PMID 35203305, 2022). "Among the biological CLL prognostic markers the IgVH mutation status or its surrogate markers (ZAP-70 and CD38 expression) as well as genomic aberrations may identify the subjects with more aggressive leukemia and poor prognosis." (PMID 27147570, 2016). "In reviewing the literature, no data was found on the association between ZAP70 gene and/or rs104893674 SNP and mixed leukemia phenotype for providing supporting or opposing ideas, nevertheless, several lines of evidence in the literature indicate other genes that have relation to both ALL and AML." (PMID 39113054, 2024). "Its high level of expression in leukemia implies that ZAP70 may be a target for leukemia therapies." (PMID 29843451, 2018). "Since human U-CLL is TC+ZAP70+CD5+, we further compared TC– and TC+Tg ATAμκTg mice by microarray analysis, to determine why TC+Tg mice showed lymphoma/leukemia development in middle age instead of old aged." (PMID 38570827, 2024). "In T-ALL cells, CCL19 activation of CCR7 was sufficient to promote the entry of the leukemia cells into the CNS and for ALL patients, in general, ZAP70 was elevated along with CCR7 and CXCR4, which was also linked to CNS spread." (PMID 35203305, 2022). "These include immunophenotypic markers of leukemia cells (CD38 and ZAP-70) assessed by flow cytometry in the immunoglobulin variable region of the heavy chain gene (IgVH)." (PMID 33147729, 2020). "The study indicates that EGCG inhibits ZAP70 activity, leading to the suppression of the CD3-mediated T cell-induced pathways in leukemia cells." (PMID 29843451, 2018). "Even after 72 h of treatment with 10 μM gefitinib, only ZAP-70+ CLL cells responded to treatment, suggesting that gefitinib only targets malignant leukemia cells expressing ZAP-70." (PMID 25275600, 2014). "In a leukemia cell line and human peripheral blood, CXCL12-induced tyrosine phosphorylation of ZAP70 and Vav1 is essential for cell migration and adhesion." (PMID 23620790, 2013).
leukemia (continued). "Similarly, MT-SLP-76 enhanced in vivo activity of CD19-4-1BBζ CAR in a model of CD19 ultra-low leukemia (600 molecules cell−1), whereas overexpression of either cytosolic SLP-76 or ZAP-70 had minimal effect." (PMID 41131392, 2025). "To confirm the necessity of tethering SLP-76 to the membrane versus overexpression of cytosolic proximal signaling molecules in vivo, we compared MT-SLP-76 to overexpression of cytosolic SLP-76 or ZAP-70 in this model and found that only MT-SLP-76 restored functionality against CD22-low leukemia." (PMID 41131392, 2025). "CAR T cells overexpressing LCK and ZAP70 showed effects in improving anti-leukemia function, but they were not as good as C-JUN overexpression." (PMID 39039086, 2024). "Similarly, ZAP70, PTPRC, FYN and WASP2 were found to be dysregulated in different cancers including breast, leukemia, colorectal cancer, etc.." (PMID 34834481, 2021).
autoimmune disease (13 papers, 2009 to 2025). A disorder resulting from loss of function or tissue destruction of an organ or multiple organs, arising from humoral or cellular immune responses of the individual to their own tissue constituents. "Given its similar pathway and risk reduction profile, ZAP70 has also emerged as a candidate for further research in the context of managing autoimmune diseases." (PMID 41238958, 2025). "Mutations of the genes encoding T cell receptor signaling molecules, such as ZAP-70, can cause T-cell mediated autoimmune diseases, including RA." (PMID 36273177, 2022). "Likewise, a subset of the ZAP70‐deficient patients described by Sharifinejad et al40 developed non‐infectious clinical manifestations, such as autoimmune disease (n = 7, 19.4%), including autoimmune cytopenias, autoimmune nephritis, and autoimmune enteropathy." (PMID 34923645, 2022). "High levels of ZAP70 expression and IL-4 secretion might be indicative of poor prognosis, and increased levels of IL-4 may be caused by infections and autoimmune diseases that accompany the disease." (PMID 26376785, 2016). "A saFRET biosensor-based high-throughput drug screening (saFRET-HTDS) assay further enables the identification of an FDA-approved cancer drug, Sunitinib, that can be repurposed to inhibit ZAP70 activity and autoimmune-disease-related T-cell activation." (PMID 34413312, 2021). "Syk and ZAP-70 are also involved in T-cell and B-cell receptor signaling potentially making Syk and ZAP-70 enzyme targets for the treatment of autoimmune diseases." (PMID 20339519, 2009). "Interestingly, both hypoactive and hyperactive ZAP70 can lead to the development of autoimmune diseases, albeit through distinct mechanisms." (PMID 34923645, 2022). "The identification of WFA-interactome associated via ZAP70, TCR, and NFκB in T-cells could be important in understanding T-cell dysfunctions acquired through prolonged exposure to TNF-α in autoimmune diseases." (PMID 34742736, 2021). "Together these results indicate that signaling through PTPN22 can influence cytokine production in T cells expressing WT ZAP70 in addition to the SKG mutation, and that this may influence susceptibility to autoimmune disease." (PMID 27288531, 2016). "Interestingly, both hypoactive and hyperactive ZAP70 may lead to the development of autoimmune diseases, albeit through distinct mechanisms." (PMID 34923645, 2022). "Consistent with findings in Zap70 mutants, the signaling defects in at least one ZAP70 substrate, LAT, can also lead to autoimmune disease." (PMID 34923645, 2022). "Consistent with the findings in Zap70 mutants, the signaling defects in ZAP70 substrate, LAT, can also lead to autoimmune diseases." (PMID 34923645, 2022).
primary immunodeficiency (10 papers, 2016 to 2025). "Zeta(ζ)-Chain Associated Protein Kinase 70 kDa (ZAP-70) deficiency is a rare autosomal recessive primary immunodeficiency disease." (PMID 37101133, 2023). "The presented patient is, to our knowledge, not only the oldest reported patient with newly diagnosed ZAP70 deficiency but also expresses a unique blended clinical phenotype and genotype with mutations linked to two distinct immune deficiency disorders." (PMID 28603521, 2017). "Among the remaining ones, it is of note the gene set linked to primary immunodeficiency given that it includes genes related to CLL biology such as Zap70, CD19, BTK and CD79A genes." (PMID 27611921, 2016). "Our results showed that ZAP70 was mapped to the primary immunodeficiency pathway in KEGG and expressed at high levels in patients with BCR." (PMID 34133324, 2021). "ZAP-70 deficiency is a rare autosomal recessive primary immunodeficiency disease with low to the absence of CD8 + T cell, most of the patients were initially diagnosed as SCID." (PMID 37101133, 2023). "In particular, we detected that ZAP70 was enriched in primary immunodeficiency, TNFRSF4, and CXCL5 were enriched in cytokine-cytokine receptor interaction, CTSG was enriched in the renin-angiotensin system, and the CHRM2 and CTSG were enriched in neuroactive ligand-receptor interaction." (PMID 34133324, 2021). "B-, T-, and NK-cell development genes were broadly inhibited (CD3, lambda 5, ZAP70, ICOS, and the B-cell linker BLNK), as were genes involved in primary immunodeficiency signaling." (PMID 40036168, 2025). "Because of epigenetic controls on primary immunodeficiency and NF-κB signaling pathway modulation, we used ChIP-qPCR to detect histone mark enrichments in the CD40 and ZAP70 genes." (PMID 40005847, 2025). "An equally high overrepresentation (OVF = 20.83, q-value = 2.38 × 10−6) was determined for the “magenta” module that was enriched in genes that control primary immunodeficiency, including ADA, CD19, CD79A, IGLL1, TAP1, TAP2, TNFRSF13C, and ZAP70." (PMID 32873298, 2020). "In addition, related primary immunodeficiency and NF-κB signaling pathway genes such as CD40 and ZAP70 significantly increase after MLT treatments in cIECs, which is in accordance with the previous study." (PMID 40005847, 2025). "Enrichment Kyoto Encyclopedia of Genes and Genomes (KEGG) analysis revealed DEGs engaged into three metabolic pathways: NF-kappa B signaling pathway (ZAP70, LCK, LTB), T cell receptor signaling pathway (ITK, ZAP70, LCK), and primary immunodeficiency (ZAP70, IL7R, LCK)." (PMID 30917529, 2019).
lymphoma (9 papers, 2012 to 2025). A malignant (clonal) proliferation of B- lymphocytes or T- lymphocytes which involves the lymph nodes, bone marrow and/or extranodal sites. "This patient was found to have a germline ZAP70 mutation that is related to lymphoma risk, and was further treated with salvage therapy and an allogeneic hematopoietic stem-cell transplant (allo-HSCT), and is still alive." (PMID 40269280, 2025). "While ZAP-70 activation through the BCR is inefficient in CLL and lymphoma cell lines and appears to be negligible compared to Syk activation, ZAP-70 can still recruit downstream signaling molecules following BCR stimulation." (PMID 22908014, 2012). "For CCR7-dependent B-ALL, CNS entry was linked to ZAP70 activation whereas, for primary central nervous system lymphoma, astrocyte-derived CCL19 retained CCR7-expressing lymphoma cells in the CNS, leading to gliosis and increased risk of gliosis-induced primary central nervous system lymphoma." (PMID 35203305, 2022). "We found increased basal levels of several phospho-proteins in lymphoma B cells, whereas they overall had impaired, but sustained anti-BCR-induced p-PLCγ, p-SYK/Zap70, p-SFKs and p-ERK, compared to healthy donor B cells." (PMID 23072591, 2012). "Since neonatal state to age with TC+Tg continuously, middle age CLL/lymphoma generation is not similar to old aged generated, however, some increased in TC+ZAP70+ are similar to the old age TC– ATA B tumor." (PMID 38570827, 2024). "In this paper, we found that RagKO ThyKO ATAμκTg mice which were TC–CD5–Thy-1– and lacked mature T and B cells, showed high ZAP70+ B1 cells with early state of CLL/lymphoma." (PMID 38570827, 2024).
Sepsis (8 papers, 2014 to 2025). Sepsis is defined as life-threatening organ dysfunction caused by a dysregulated host response to infection. "In our study, ZAP70 was differentially expressed in nine sepsis datasets and validated through genetic-based MReQTL and SMR analyses." (PMID 40761792, 2025). "Our analysis, even after adjustment for the subject effects in the baboon sepsis models, revealed as well that an intracellular signaling molecule, ZAP70, was downregulated after induction of sepsis, especially in the E. coli model." (PMID 37261908, 2023). "The role of ZAP70 in adult sepsis warrants further investigation." (PMID 33132754, 2020). "Mechanistically, we demonstrate that MMP9 suppresses NFAT activation by impairing TCR signaling via Lair-1-mediated ZAP70 inhibition and by disrupting CRAC-channel-dependent calcium influx—interactions previously unrecognized in the context of sepsis." (PMID 41306770, 2025). "Both ZAP70 and NME4 showed the strongest binding affinity for lumichrome, highlighting the potential relevance of this metabolite in sepsis-induced immunosuppression." (PMID 40761792, 2025). "Accordingly, high levels of ZAP70 were inversely correlated with organ failure (SOFA) scores and mortality in patients with sepsis." (PMID 37261908, 2023). "Downregulated genes in sepsis Th2 cells were significantly overrepresented in processes related to viral responses (including TNFRSF25 and GIMAP5; -0.79 and -0.49log2FC, respectively) and differentiation (ZAP70; -0.66log2FC)." (PMID 41208955, 2025). "ZAP70, a critical tyrosine kinase involved in T cell activation following T cell receptor (TCR) engagement, has been identified as a potential biomarker for sepsis in multiple bioinformatics studies." (PMID 40761792, 2025). "Furthermore, we observed that in both baboon sepsis models, 3 other miR-93-5p targets, ZAP70, MAP3K3, and MAP4K2, were downregulated after induction of sepsis." (PMID 37261908, 2023). "The acute phosphorylation/activation of ZAP-70, LAT, Erk or Akt in response to stimulation with immobilised or soluble CD3 and CD28 mAb was indistinguishable between control and any of the SIRS/sepsis groups." (PMID 25541945, 2014).
prostate carcinoma (7 papers, 2018 to 2025). A carcinoma that arises from epithelial cells of the prostate gland. "Increasing expression levels of this miR inhibits metastasis and invasion of prostate cancer cells by inhibiting Zeta-chain-associated protein kinase 70 (ZAP70)." (PMID 38674157, 2024). "According to the literature, ZAP70 stimulates cell migration and invasion of prostate cancer cell lines." (PMID 40005847, 2025). "MiR-631 was shown to target the 3′-UTR of ZAP70 mRNA and inhibit the expression of ZAP70, thereby inhibiting prostate cancer cell migration and invasion." (PMID 34133324, 2021). "Hsa-miR-631 inhibits the migration and invasion of prostate cancer cells by targeting ZAP70 and resensitizes bortezomib-resistant multiple myeloma cells through the inhibition of UbcH10." (PMID 29755664, 2018). "ZAP70 mediated migration and invasion of prostate cancer cells." (PMID 35477402, 2022). "Combined with previous studies, we speculated that ZAP70 might not only be an important regulator of cancer metastasis but also useful in predicting the BCR in patients with prostate cancer." (PMID 34133324, 2021). "The protease-related gene ZAP70 mediates prostate cancer metastasis through the NF-κB pathway." (PMID 33330624, 2020). "Studies have suggested that ZAP70 is a potential therapeutic target in the tumor microenvironment (TME) and may influence the prognosis of prostate cancer and bladder cancer." (PMID 40104395, 2025).
COVID-19 (6 papers, 2021 to 2024). A disease caused by infection with severe acute respiratory syndrome coronavirus 2. "In the present study, TREM-2 interacted with CD3ζ/ZAP70 complex in T cells, and this interaction was strengthened in patients with COVID-19 compared to healthy donors." (PMID 34878838, 2021). "We found that M protein bound to TREM-2/CD3ζ/ZAP70 complex, and this binding was increased in the lung of patients with COVID-19 versus healthy controls." (PMID 34878838, 2021). "Together, these data suggested that TREM-2 bound to SARS-CoV-2 M protein and interacted with CD3ζ/ZAP70 complex in T cells during COVID-19." (PMID 34878838, 2021). "We demonstrate in this Brief Report the effect of adding C24D to PBMCs obtained from ten hospitalized COVID-19 patients on the phosphorylation of Lck, ZAP-70 and VAV-1 proteins in the CD45 signaling pathway." (PMID 34414199, 2021). "Furthermore, the binding of M protein and TREM-2/CD3ζ/ZAP70 complex was confirmed by IP in COVID-19 lung, which was accumulated with abundant TREM-2+CD4+ T cells." (PMID 34878838, 2021). "Moreover, we found that the binding of TREM-2 and CD3ζ/ZAP70 complex was enhanced in T cells of patients with COVID-19 versus healthy controls and increased in T cells from severe versus nonsevere patients." (PMID 34878838, 2021). "This could explain why we detected the binding of M protein with TREM-2 and CD3ζ as well as ZAP70 in the lung tissue of patients with COVID-19, where abundant infiltrating TREM-2+CD4+ T cells were found." (PMID 34878838, 2021). "In this short report, we demonstrated that treatment of PBMCs from ten hospitalized COVID-19 patients with C24D resulted in the reactivation of CD45 key-signaling molecules: Lck, ZAP-70 and VAV-1." (PMID 34414199, 2021). "Both M protein and anti-CD3 Ab induced CD3ζ (Tyr83), ZAP70 (Tyr319), and STAT1 (Ser727) phosphorylation in COVID-19 CD4+ T cells." (PMID 34878838, 2021). "TREM-2–Fc fusion protein, used to block the interaction between TREM-2 and M protein, reduced the phosphorylation of CD3ζ (Tyr83) and ZAP70 (Tyr319) in CD4+ T cells of patients with COVID-19 upon pseudovirus–M protein stimulation, whereas control IgG did not affect the phosphorylation of CD3ζ/ZAP70." (PMID 34878838, 2021). "LAT, VAV1, ZAP70, and CARD11, as the key components of T-cell receptor, exhibited a significant decrease with severity in COVID-19, negative with G004246 and CATG00000032642.1." (PMID 35573725, 2022). "Higher levels of phosphorylated CD3ζ (Tyr83) and ZAP70 (Tyr319) were detected in pseudovirus–M protein–stimulated TREM-2+CD4+ T cells from patients with COVID-19 compared with TREM-2− groups, whereas pseudovirus vector did not induce the phosphorylations of CD3ζ and ZAP70 in TREM-2+CD4+T cells." (PMID 34878838, 2021).
breast carcinoma (5 papers, 2007 to 2023). "In BL1, the enriched kinases, such as LCK and PTK2B, were associated with tumorigenesis, as well as invasion of breast cancer, whereas ZAP70 was reported to be related to drug resistance in TNBC." (PMID 36672350, 2023). "FGR and ZAP70 have diagnostic and therapeutic potential due to their relationship with breast cancer development and progression." (PMID 27911271, 2017). "Similarly, a longitudinal study focused on immunologic system effects of adjuvant chemotherapy and radiotherapy in breast cancer showed that regulatory T cells and ZAP70 remain in their low grade forms after adjuvant chemoradiotherapy." (PMID 34414195, 2021). "Zap70 showed a significant upregulation in T cells in patients before treatment, compared to healthy volunteer, which further contributed to the defective T-cell function in breast cancer patients." (PMID 17551492, 2007). "EGCG interacts with target proteins in the breast cancer cells, such as ERα, Zap-70, PI3K, G3BP1, IGF-1R, vimentin, Bcl-2, Bcl-xL, GRP78, and Fyn via hydrogen bonding, which plays a role in the inhibition of breast cancer." (PMID 27483305, 2016).